APOB (apolipoprotein B)
Diseases named in the same sentence as APOB in open-access papers (continued):
Sharing a sentence is not in itself a finding about the gene and the disease.
coronary atherosclerosis (continued). "At the same time, atherogenic lipoproteins that have been identified, the high apoliprotein B, low apolipoprotein A-1 and the high ratio of apoB: apoA1 also affect the formation and progression of coronary atherosclerosis." (PMID 30134981, 2018). "The logistic regression analysis showed a significant association between residual apoB and the presence of coronary atherosclerosis; however, statistical significance was not reached for S-CAD (p = 0.089)." (PMID 41374382, 2025). "In the only study that we could find, residual apoB correlated with both coronary atherosclerosis and its burden, patients being evaluated via computed tomography angiography." (PMID 41374382, 2025). "Moreover, TG-rich-ApoB within the coronary wall is considered as an important pathogenesis of coronary atherosclerosis." (PMID 38313836, 2023). "However, few real-world evidence studies assessed the relationship between apoB levels and progression of coronary atherosclerosis." (PMID 37559117, 2023). "The generalized linear model and relative risk regression (generalized linear Poisson model with robust error variance) were used to analyze the association of the levels of apoB and LDL-C with the severity of coronary atherosclerosis and residual risk of coronary atherosclerotic heart disease." (PMID 35573992, 2022). "Higher levels of apoB were significantly associated with residual risk of coronary atherosclerotic heart disease and severity of coronary atherosclerosis in statin-treated participants, whereas no such associations were found for elevated levels of LDL-C." (PMID 35573992, 2022). "We observed significant associations of higher levels of apoB with residual risk of coronary atherosclerotic heart disease and severity of coronary atherosclerosis in statin-treated participants, but not in LDL-C." (PMID 35573992, 2022). "We conducted this research to determine whether the concentrations of apoB and LDL-C are still associated with the severity of coronary atherosclerosis in participants with statin treatment." (PMID 35573992, 2022). "An increase in the serum apoB/A-I ratio was associated with significant coronary atherosclerosis independent of conventional risk factors." (PMID 28957410, 2017). "The genetic prediction of the ApoB/ApoA1 ratio was significantly positively correlated with diseases like IHD, coronary atherosclerosis, angina pectoris, unstable angina pectoris, and MI." (PMID 38310324, 2024). "However, considering the potential value of ApoB/ApoA1 ratio in predicting IHD, our study analyzed its common representative diseases, such as coronary atherosclerosis, angina pectoris and ACS (including unstable angina pectoris and MI)." (PMID 38310324, 2024). "Categorizing apoB and LDL-C based on tertiles, higher levels of apoB were significantly associated with the severity of coronary atherosclerosis (Ptrend = 0.012), whereas no such associations were found for elevated levels of LDL-C (Ptrend = 0.585)." (PMID 35573992, 2022). "In our comparative analysis, we observed that the mean values of a portion of traditional lipid markers (TC, LDL-C, and non-HDL-C) and apoB increased progressively and significantly across the three studied groups; however, apoB proved to be a more sensitive indicator of coronary atherosclerosis." (PMID 41374382, 2025).
Hyperinsulinemia (27 papers, 2011 to 2025). An increased concentration of insulin in the blood. "In states of chronic systemic hyperinsulinemia, the loss of responsiveness to insulin-targeting of apoB for degradation together with increased fatty acid flux to the liver, and increased DNL, results in increased VLDL secretion." (PMID 32187264, 2020). "Adjusting the association of plasma apoB to hyperinsulinemia and IR for IL-1Ra eliminated these associations." (PMID 26417659, 2015). "Plasma apoB is associated with hyperinsulinemia and IR in normoglycemic obese subjects, which is eliminated upon adjustment for plasma IL-1Ra." (PMID 26417659, 2015). "Plasma IL-1Ra associated with plasma IL-1β (r=0.40), and more strongly with hyperinsulinemia and IR than apoB, while the association of plasma IL-1β was limited to second phase and total insulin secretion (r=0.23)." (PMID 26417659, 2015). "Finally, adjusting the association of plasma apoB with IR and hyperinsulinemia for plasma IL-1Ra eliminated this association, suggesting the involvement of the IL-1 family in vivo." (PMID 26417659, 2015). "Thus, simultaneous measurement and interpretation of WC and fasting TG can be a powerful tool to identify both men and women characterized by the atherogenic triade (hyperinsulinemia, elevated apolipoprotein B, and small, dense LDL-C) and at high risk for CAD." (PMID 24558974, 2014). "Of note, while it cannot be excluded that the association of plasma apoB with hyperinsulinemia and IR may also be related to increased production of IL-1α, which promotes IL-1Ra secretion, IL-1α is rarely found in circulation and its role in T2D in humans is less clear." (PMID 26417659, 2015). "Hyperinsulinemia inhibits microsomal triglyceride protein expression which is crucial in the regulation of apolipoprotein B-100 and VLDL production." (PMID 30881692, 2019). "The previous studies verified that the HTGW phenotype could be used as an inexpensive screening tool to identify individuals characterized by the atherogenic metabolic triad (hyperinsulinemia, elevated apolipoprotein B, and small dense LDL-C particles)." (PMID 35990944, 2022). "Nevertheless, to verify that the association of plasma apoB to hyperinsulinemia, IR and plasma IL-1Ra was independent of adiposity, we used a partial correlation analysis." (PMID 26417659, 2015). "We examined whether the relation of plasma apoB to hyperinsulinemia and IR was dependent on the IL-1 family by two methods." (PMID 26417659, 2015). "In conclusion, elevated plasma apoB associates with hyperinsulinemia and IR independent of adiposity in normoglycemic overweight and obese subjects." (PMID 26417659, 2015). "Furthermore, hyperinsulinemia decreases apolipoprotein-B synthesis and consequently very low-density lipoproteins (VLDL)-associated lipid export from liver cells, leading to hepatic triglyceride synthesis with concomitant inhibition of triglyceride secretion as very low-density lipoproteins (VLDL)." (PMID 37938366, 2024). "Nevertheless, despite these sex differences, the association of plasma apoB with IR and hyperinsulinemia was independent of sex or body composition and may be related to the effects of apoB-lipoproteins per se." (PMID 26417659, 2015). "The first proposed mechanism was that iron induced hyperinsulinemia and IR, which in turn contributed to unfavorable TG, LDL-C, TC, and non-HDL-C, and hepatic IR accelerated the synthesis and secretion of apoB through protein-tyrosine phosphatase 1B." (PMID 33659229, 2021). "This suggests that the relation of plasma apoB to plasma IL-1Ra, hyperinsulinemia and IR is, in general, independent of body composition in this population." (PMID 26417659, 2015).
COVID-19 (24 papers, 2020 to 2025). A disease caused by infection with severe acute respiratory syndrome coronavirus 2. "A weaker, yet still observable, association was found for other factors such as C-peptide, ApoB, COVID-19 severity, T2D duration, IL-6, cholesterol, and BMI." (PMID 40950970, 2025). "The most influential variables across the top 10 models included telomere length, HbA1c, vitamin D3, waist circumference, ApoA1, C peptide, ApoB, COVID-19 severity, duration of T2D, IL-6, cholesterol, BMI, and age." (PMID 40950970, 2025). "APOB has been observed to be upregulated in enterovirus 71 infection and displays elevated levels in the blood of COVID-19 patients." (PMID 35438176, 2022). "Although the cholesterol metabolism pathway was significantly downregulated (including APOA2, APOC1, APOH, CETP, and APOA4), the increased levels of PCSK9 and APOB suggested the dysregulation of cholesterol metabolism in severe and critical COVID-19 patients." (PMID 35958562, 2022). "The study of LDL metabolism revealed higher concentrations of apoprotein B (ApoB) in COVID-19 patients (p = 0.03), while LDL cholesterol levels and particle size were not different in the two groups." (PMID 34031519, 2021). "The high levels of APOB in the plasma might indicate significant cardiovascular manifestation seen in COVID-19 infected severe patients." (PMID 33995121, 2021). "We carefully observed the substantial differences in several metabolites between LTCS and severe acute COVID-19 patients, including HDL cholesterol and apolipoprotein B100 Apo-B (TPAB)." (PMID 37228606, 2023). "This apolipoprotein is primarily carried by TRLs, where it serves as a ligand for the ApoB/ApoE receptor (LDL receptor), which also supports the increase in TG during COVID-19." (PMID 36902035, 2023). "Three lipoprotein main fraction parameters, i.e. TG-HDL, Chol-LDL and ApoB-VLDL show significantly different concentrations between COVID-19≤21 and Post COVID-19 groups, and a medium Cliff’s delta effect size, S6 Fig and S3 Table." (PMID 35446921, 2022). "Pathways depicting cholesterol, HDL and LDL metabolism (WP430, WP5109, WP4522, WP3601) are also among the top 10 pathways that have reduced activity in COVID-19 patients with significant reductions in APOA1, APOA2, APOC2, APOC3, APOB protein abundance." (PMID 36189295, 2022). "The study included fifty COVID-19 patients admitted to the intensive care unit (ICU) and found that apolipoprotein A1 and apolipoprotein B were significantly decreased in severe COVID-19 patients compared to non-severe patients." (PMID 38802549, 2024). "The validation study using MRM could specifically detect AGT, FGG, APOB, SERPING1, and SERPINA3 host peptides in COVID-19 severe patients." (PMID 33995121, 2021). "In particular, ApoB, VLDL, and IDL particles, smaller-sized VLDL fractions (VLDL-2, -3, and -4), and IDL-bound lipids in cholesterol, triglycerides, and phospholipids were significantly different for COVID-19 compared with CS." (PMID 34938772, 2021). "Moreover, the arylesterase (AE) activity of PON1 and the anti-oxidative (AO)-capacity of apoB-depleted serum were also lower in COVID-19 patients (p = 0.034, p < 0.001) when compared to non-COVID-19 pneumonia patients." (PMID 36290581, 2022). "Serum levels of apoA-1 and apoB did not correlate with COVID-19 severity." (PMID 35676519, 2022). "Moreover, ApoB bound to VLDL and IDL were further increased in COVID-19 patients." (PMID 34938772, 2021).
acute coronary syndrome (23 papers, 2006 to 2026). Signs and symptoms related to acute ischemia of the myocardium secondary to coronary artery disease. "We found a strong positive correlation of both Apo B and ApoB/ApoA1 in predicting high Gensini scores (scores ≥ 47) in patients who suffered from acute coronary syndromes (P value <0.001)." (PMID 33725226, 2021). "Similarly, another study involving 160 participants (80 with acute coronary syndrome and 80 controls) confirmed a strong correlation between apoB, apoA, and apoB/A ratio with acute coronary syndrome incidence." (PMID 40852379, 2025). "Apolipoprotein B/apolipoprotein A-I ratio is a useful tool of risk assessment in patients presenting with non-ST segment elevation acute coronary syndrome including prediction of coronary multivessel affection." (PMID 32449038, 2020). "The current study aimed at exploring the diagnostic and short-term prognostic values of apolipoprotein B/apolipoprotein A-I ratio in patients presenting with non-ST segment elevation acute coronary syndrome." (PMID 32449038, 2020). "Accumulating data suggest that apoB/apoA-I ratio could be a predictor of acute coronary syndromes in addition to the well-known elevated LDL-C and plasma total cholesterol/high-density lipoprotein cholesterol ratio as strong predictors of cardiovascular disease." (PMID 32449038, 2020). "The non-ST segment elevation acute coronary syndrome group showed significantly unfavorable lipid profile parameters, including apolipoprotein B/apolipoprotein A-I ratio." (PMID 32449038, 2020). "Several smaller studies measuring levels in AMI or acute coronary syndromes (ACS) have shown similar findings with either AMI or prognosis following ACS with a variety of IgM OSE markers, including oxidized cardiolipin, phosphocholine, and apoB-immune complexes." (PMID 37211249, 2023).
depression (22 papers, 2013 to 2025). "SHAP analysis revealed that the ApoB and gTyG indices were the most important predictors, with higher levels correlating with a greater risk of depression." (PMID 41458557, 2025). "This study demonstrated that the ApoB and gTyG index are robust biomarkers for predicting depression risk in CHF patients." (PMID 41458557, 2025). "Our results demonstrate that biomarkers such as the ApoB and gTyG indices play critical roles in predicting depression risk in CHF patients." (PMID 41458557, 2025). "In the context of CHF follow-up, the integration of simple thresholds for the ApoB and gTyG indices can facilitate the identification of individuals at high risk for depression at an early stage." (PMID 41458557, 2025). "Both apolipoprotein B and triglycerides are linked to oxidative stress, which accelerates cellular damage and inflammation, likewise connecting depression." (PMID 40599634, 2025). "In this study, we developed and evaluated several ML models to predict depression risk in patients with CHF using key biomarkers such as ApoB, the gTyG index, and other clinical features." (PMID 41458557, 2025). "In this analysis, we also found a high LDL-C, TC, ApoB, and ApoB/ApoA-I ratio to be associated with a lower risk of depression, anxiety, and stress-related disorders, collectively or individually (eTable 6 in Supplement 1)." (PMID 38564219, 2024). "Elevated ApoB and gTyG indices were strongly associated with depression risk in both the unadjusted and fully adjusted models (ApoB Q4 vs. Q1: OR 5.41, 95% CI 3.72–7.87; gTyG Q4 vs. Q1: OR 2.88, 95% CI 1.88–4.41; both P < 0.001), demonstrating clear nonlinear dose–response relationships." (PMID 41458557, 2025). "Although ApoB and the gTyG index were identified as key predictors of depression risk in CHF patients, the biological or pathway-level relationships between these biomarkers remain unclear." (PMID 41458557, 2025). "In addition to its cardiovascular implications, recent studies have revealed associations between ApoB and psychiatric conditions, particularly depression." (PMID 41458557, 2025). "Risk ratios of depression across ApoB levels in different models." (PMID 41458557, 2025). "As the levels of ApoB and the gTyG index increase, the risk of depression also increases." (PMID 41458557, 2025). "Using ApoB quartiles as the independent variable, logistic regression showed that compared with Q1, the risk ratios for depression were 1.53, 3.00, and 7.90 in Q2–Q4 in the unadjusted model, and 1.26, 2.26, and 5.41 in the fully adjusted model (all P < 0.001 for Q3–Q4)." (PMID 41458557, 2025). "Our results revealed that higher levels of the ApoB and gTyG indices were significantly associated with an increased risk of depression, with odds ratios for ApoB Q2, Q3, and Q4 being 1.53, 3.00, and 7.90 times higher than those of the Q1 group, respectively (P < 0.001)." (PMID 41458557, 2025). "A pooled analysis of 230 metabolic markers in patients with depression revealed an atherogenic lipid profile in depression, marked by increased very low‐density lipoprotein, triglycerides, and ApoB alongside decreased high‐density lipoprotein." (PMID 41458557, 2025). "The results show that ApoB is the core predictor for depression in CHF patients, while the gTyG index contributes significantly to the model’s predictive ability, ranking second." (PMID 41458557, 2025). "One study reported that depression predicts an increase in ApoB, and another reported that increased ApoB increases the odds of depression." (PMID 41458557, 2025). "Representative individual waterfall plots show that the ApoB and gTyG indices are the primary factors influencing the occurrence of depression in CHF patients." (PMID 41458557, 2025). "Another study has examined ApoA and ApoB levels in major depressive disorder (MDD), revealing that severity of depression correlated to higher ApoB and inversely to ApoA." (PMID 38673634, 2024).
depression (continued). "Patients with depression, anxiety, or stress-related disorders also had higher levels of ApoA-I and ApoB during the 10 years before diagnosis compared with controls." (PMID 38564219, 2024). "In contrast, in the temporal trend analysis, we observed that individuals with the studied psychiatric disorders, especially depression, demonstrated elevated levels of ApoA-I and ApoB during the 10 years before diagnosis." (PMID 38564219, 2024). "Depression is considered a metabolic disease related to liver function, and it has been shown that apolipoprotein B, very-low-density lipoprotein cholesterol, triglycerides, unsaturated fatty acids, tyrosine and abnormal metabolism are related to depression." (PMID 36979246, 2023). "This study examines cognitive deficits, and the correlation of serum ApoB levels with cognitive deficits of depressive disorder." (PMID 28054633, 2017). "Restricted cubic spline analyses further revealed significant nonlinear associations between ApoB and depression risk in both unadjusted and adjusted models (P for nonlinearity < 0.001)." (PMID 41458557, 2025). "Some studies report that depression is linked to decreased HDL cholesterol and apolipoprotein A, alongside increased LDL cholesterol and apolipoprotein B. However, a meta-analysis by Persons and Fiedorowicz found a negative correlation between depression and LDL cholesterol." (PMID 40563330, 2025). "Fasting glucose, overweight, hip circumference, depression, insomnia, and sleep apnea showed no genetic association with changes in the ApoB/ApoA1 ratio." (PMID 38310324, 2024). "The purpose of the present study is to examine whether depressive patients have worse cognitive functions than healthy controls, and to further investigate whether serum ApoB levels contribute to cognitive deficits of depressive disorder." (PMID 28054633, 2017). "We find the effect of higher serum ApoB levels on delayed memory decline of depressive disorder." (PMID 28054633, 2017). "Interestingly, this study was the first to find that serum ApoB levels were negatively correlated with delayed memory decline of depressive disorder." (PMID 28054633, 2017). "Interestingly, we found within the top 20 upregulated DEGs in the S+ larvae the gene apobb.2, codying for the apolipoprotein B (ApoB) which overexpression has been positively correlated to neurodegeneration, cognitive deficits, and depression in humans and animal models." (PMID 37013516, 2023). "Other biomarkers, including phospholipids in very large HDL and apolipoprotein B, further support the hypothesis that lipid metabolism may be a central mechanism in CVD–depression comorbidity." (PMID 41133925, 2025). "However, no studies have examined the correlation between serum ApoB levels with cognitive deficits of depressive disorder." (PMID 28054633, 2017). "The smoking index, platelet counts, plateletcrit, NEUT%, TC, triglyceride, LDL-C, apolipoprotein B, BUN, creatinine, cystatin-C, BNP and HAM-D24 score were significantly higher in heart failure patients with depression when compare with those without depression." (PMID 27955661, 2016).